INS (insulin)
Diseases named in the same sentence as INS in open-access papers (continued):
Sharing a sentence is not in itself a finding about the gene and the disease.
Autoimmunity (continued). "T1DM is recognized as an autoimmune condition that necessitates lifelong insulin therapy upon diagnosis, and it predominantly affects children and adolescents." (PMID 39649224, 2024). "Since the autoimmune status of a patient predicts their long-term need for insulin, autoimmunity against β-cells must also be evaluated." (PMID 39634998, 2024). "Despite the appearance of autoimmunity and dysglycemia during Stages 1 and 2 T1D, there is still sufficient and functional pancreatic β‐cell mass to prevent the necessity for insulin treatment." (PMID 38129973, 2024). "Prior studies in mice, human pancreas tissue, and humans suggest that ER stress in islet β cells contributes to both cellular dysfunction (reduced insulin secretion) and the production of neoantigens that trigger autoimmunity." (PMID 38889047, 2024). "In the context of autoimmunity in T1D, oxPTMs and their immunological consequences have been studied extensively; however, cellular response to oxidized insulin regarding INSR and GLUT4 regulation, metabolism, proliferation, and glucose uptake were omitted." (PMID 39378614, 2024). "While T1D is an autoimmune disorder that needs continuous insulin replacement therapy, T2D can be prevented by dietary and lifestyle changes." (PMID 38540730, 2024). "It has also been shown that deceased autoimmune diabetic children express HLA-DR in islets containing only insulin-producing cells, suggesting that β-cells are an islet endocrine cell type that uniquely expresses MHC-II." (PMID 39211046, 2024). "The citrullination of pancreatic glucokinase (GK) as a result of inflammation further triggers autoimmunity and influences GK activity to suppress insulin secretion." (PMID 38540730, 2024). "T1DM is a T-cell-mediated, organ-specific autoimmune disorder which is characterized by beta-cell destruction and decreased insulin production." (PMID 39120188, 2024). "Here, we investigated consequences of insulin exposure for T cell function in the canonical autoimmunity of rheumatoid arthritis (RA)." (PMID 39768214, 2024). "T1DM arises due to autoimmunity against beta cells, which generate insulin, leading to severely reduced insulin levels." (PMID 37779807, 2023). "The partial remission (PR) phase of type 1 diabetes (T1D) is an underexplored period characterized by endogenous insulin production and downmodulated autoimmunity." (PMID 36960962, 2023). "It is unclear why insulin is the key antigen in the early autoimmunity period and why newly emerging autoimmunity to insulin declines with age." (PMID 37231274, 2023). "This is supported by Daniel and colleagues, who showed that the number of insulin-specific regulatory T cells (Tregs) increases with age and with the duration of autoimmunity." (PMID 37231274, 2023). "T1D is the clinical outcome of a relapsing-remitting T-cell driven autoimmunity that, across three stages, gradually impairs and damages a mass of pancreatic β cells that requires exogenous insulin replacement to maintain normoglycemia." (PMID 37388741, 2023). "Early autoimmunity is directed against insulin, and memory insulin-reactive T cell responses and IAA have a similar temporal appearance." (PMID 37231274, 2023). "There was an impressive study in Brazil in which autoimmunity in T1D was aggressively treated with autologous stem cell transplants, and when partial or complete remission was obtained insulin levels were impressively increased." (PMID 37409234, 2023). "In vitro studies and both T1D and T2D animal models showed that vitamin D can improve glucose homeostasis by enhancing insulin secretion, reducing inflammation, reducing autoimmunity, preserving beta cell mass, and sensitizing insulin action." (PMID 37111216, 2023). "Second, serum from nonobese diabetic (NOD) mice, a polygenic model of pancreas-specific autoimmunity, was enriched in peptides derived from both insulin and predicted pancreatic proteins." (PMID 37934865, 2023).
Autoimmunity (continued). "T1DM is an autoimmune disorder necessitating insulin therapy since insulin-producing beta cells are lost." (PMID 38034250, 2023). "Of note, while we focus on only a few conditions, it is plausible that any condition involving an immune response, including autoimmunity, would have relevant insulin-immune interactions." (PMID 36992811, 2023). "Results from (pre)clinical studies are highlighted that explore restoration of insulin production and reduction of autoimmunity." (PMID 35903316, 2022). "T1D mouse models showed that insulin acts as an essential autoantigen, which highlights the effects of insulin in initiating T1D autoimmunity." (PMID 35720417, 2022). "T1D is a health problem characterized by autoimmunity and the destruction of pancreatic cells that produce insulin." (PMID 36411933, 2022). "The discovery of autoantibodies against beta-cell antigens indicates the onset of autoimmunity targeting insulin-producing cells." (PMID 36420297, 2022). "T1DM is an autoimmune disorder, characterized by T cell-mediated destruction of insulin-producing beta cells in the pancreas, resulting in a reliance on exogenous insulin throughout life." (PMID 35242797, 2022). "Beneficial effects of this treatment have been observed in terms of autoimmunity, β-cell function, and insulin dependency, with some patients remaining insulin independent for several years." (PMID 36611906, 2022). "Typically, T1D is thought to occur as a result of autoimmunity toward islets of Langerhans, resulting in the destruction of insulin-producing cells (β cells) and thus lifelong reliance on exogenous insulin." (PMID 34489972, 2021). "Here, oral insulin was given as antigen-specific immunotherapy before the onset of autoimmunity in children from age 6 months to assess its safety and immune response actions on immunity and the gut microbiome." (PMID 33515070, 2021). "Thrombocytopenia due to DM patients is commonly related to medications given to patients like insulin and autoimmunity to bone marrow cells." (PMID 34074308, 2021). "NOD mice spontaneously develop autoimmunity targeting lacrimal and salivary glands (SS-like manifestations) and insulin-producing β cells in the endocrine pancreas (T1D manifestations)." (PMID 33322152, 2020). "Random plasma C-peptide concentrations and pancreatic insulin content at therapy initiation revealed significant heterogeneity in autoimmune diabetic mice, depending on disease duration." (PMID 32582188, 2020). "T1DM these anti‐insulin antibodies targeted as foreign particle as shows autoimmunity against its own proteins." (PMID 32142224, 2020). "Based on current knowledge, one can create a model over LADA development where the first step in disease development is genetically triggered autoimmunity that slowly destroys the beta-cells and reduces insulin release." (PMID 30971952, 2019). "The recurrence of autoimmunity, resulting in the destruction of the de novo insulin expressing tissue, is an obvious concern." (PMID 30514969, 2019). "For example, insulin cfDNA reflects beta-cell death and is elevated in response to autoimmunity in NOD mice, recent-onset T1D, and islet transplant 24 h after islet infusion." (PMID 31795194, 2019). "Regarding islets, syngeneic CD45− splenic stem cells infused into NOD mice migrated into islets damaged as a result of autoimmunity and differentiated into insulin-positive β cells." (PMID 29735923, 2018). "Pancreatic Autoimmunity is defined as the presence of autoantibodies and more frequent need for insulin treatment." (PMID 30346951, 2018). "Initial clinical suspicion of IAS can avoid unnecessary expenses involving imaging examinations and/or invasive surgical procedures, and patients must be screened for autoimmunity-related drugs for insulin." (PMID 30462811, 2018).
Autoimmunity (continued). "The mechanisms involved in autoimmunity during the pathogenesis of T1D include factors of humoral immunity, such as the presence of circulating autoantibodies (anti-insulin, among other islet autoantibodies), that can be used as biomarkers of the disease." (PMID 30050502, 2018). "In particular, the existence of insulin+/CK-19+ cells has been previously shown in the ducts of transplanted pancreas, specifically in T1D patients with recurrent autoimmunity." (PMID 29068419, 2017). "Awareness of autoimmunity will result in timely initiation of insulin in these cases specifically and will not only prevent acute metabolic decompensation but also impact development of chronic vascular complications." (PMID 28573146, 2017). "Pancreas and islet transplantation have been attractive therapeutic approaches; however, transplants containing insulin-producing cells are vulnerable to both recurrent autoimmunity and conventional allograft rejection." (PMID 29259578, 2017). "Robust titers of anti-VP1 antibodies were observed in the cord blood of the majority of children who developed insulin autoimmunity." (PMID 27604323, 2016). "C-peptide is nearly undetectable in patients with T1DM and even in patients with T2DM patients, depending on the level of residual endogenous insulin production, duration of DM, honeymoon period, drug treatment, degree of autoimmunity, and IR." (PMID 27992493, 2016). "We propose that a confluence of BCR affinity, pancreas environment, and B cell tolerance-regulating genes in the NOD animal allows acquisition of insulin and autoimmunity." (PMID 27834793, 2016). "Positive serum autoantibodies to pancreatic islet antigens: insulin (IAA), glutamic acid decarboxylase (GADA) and insulinoma-associated protein 2 (IA-2A) are hallmarks of beta cell-directed autoimmunity, and were studied in the AAD cohorts in the past." (PMID 26972575, 2016). "In contrast to the ‘classic’ pathway seen in infancy, in which the first autoantibodies are generally directed against insulin, this alternative route appears to start with autoimmunity directed against GAD." (PMID 26676824, 2016). "We have shown that residual endogenous insulin secretion and persistent autoimmunity occur more than a decade after diagnosis in patients with proven autoimmune-mediated type 1 diabetes." (PMID 27591853, 2016). "Antibody responses that were anti-VP2 competent but anti-VP1 deficient were unable to neutralize CVB, and were characteristic of children who developed early insulin-targeting autoimmunity, suggesting an impaired ability to clear CVB in early childhood." (PMID 27604323, 2016). "Here, we provide novel conceptual evidence for using low doses of strong-agonistic insulin mimetopes for efficient human Foxp3+Treg induction and suppression of human autoimmunity." (PMID 26975663, 2016). "Retrogenic NOD strains expressing Vα5D-4 α chains with many different CDR3 sequences show that even those derived from TCRs recognizing islet-irrelevant molecules develop anti-insulin autoimmunity." (PMID 23691517, 2013). "Although Ins2 is expressed at low levels in rare mTECs, thymic (pro)insulin has an essential role in protecting islet β cells against diabetogenic autoimmunity." (PMID 24137108, 2013). "TRAV13-1, the human ortholog of murine TRAV5D-4, was also capable of inducing in vivo anti-insulin autoimmunity in the NOD mouse." (PMID 23691517, 2013). "Humoral autoimmunity against insulin, first described in 1983 is established but needs to be better defined." (PMID 22567309, 2012). "The reader is referred to the following reviews where insulin autoimmunity in T1D or in the insulin autoimmune syndrome has previously been reviewed." (PMID 22567309, 2012). "Both direct evidence in the mouse and indirect evidence in the human point at insulin as a key autoantigen in T1D autoimmunity." (PMID 21785617, 2011).
Autoimmunity (continued). "Remarkable features in human T1D are the long preclinical phase that precedes the development of full-blown hyperglycemia and the high recurrence level of autoimmunity in long-standing patients who have been treated with exogenous insulin for years." (PMID 21785617, 2011). "This compelling need brings a sense of urgency to find a cure for T1D that can not only overcome the shortage of insulin-producing β-cells, but also halt the progression of autoimmunity." (PMID 19156219, 2009). "Type 1 diabetes (T1D) is an autoimmune disorder resulting from destruction of the insulin-producing β cells of the pancreas." (PMID 17697317, 2007). "In addition to age and BMI, women who require exogenous insulin during pregnancy or have a history of autoimmune conditions should be closely monitored in the years following delivery." (PMID 40076938, 2025). "It is suggested that carbonyl modified P4Hb may be a potential target of autoimmunity and enhance the immune response towards proinsulin and insulin." (PMID 40028329, 2025). "However, current research has suggested that modified antigens play a critical role in the autoimmunity characteristic of T1D, with insulin potentially being the predominant autoantigen." (PMID 40028329, 2025). "Insulin autoantibodies may also be detectable in insulin-naïve individuals that have autoimmune disorders." (PMID 40821816, 2025). "Moreover, autoimmunity altered the sensitivity of IR, reduced insulin sensitivity decreases the expression of GLUT." (PMID 40126146, 2025). "T1D is an autoimmune disorder caused by the destruction of insulin‐producing β cells in the pancreatic islets, typically resulting in a significant lack of endogenous insulin, and lifelong insulin therapy is needed for survival." (PMID 40919135, 2025). "From its earliest recognition as a polyuric wasting disease in antiquity, through its reclassification as a metabolic disorder in the insulin era, to its current status as a prototype of organ-specific autoimmunity, T1DM went through profound ontological shifts." (PMID 40725617, 2025). "Insulin (INS) is the primary and earliest target of autoimmunity in T1DM." (PMID 41373714, 2025). "Then we thought that the patient may have an autoimmune IRS due to autoantibodies against INSR (type B IRS) or exogenous insulin." (PMID 40696585, 2025). "T cells reactive to INS-DRiP epitopes are part of the normal T cell repertoire and are believed to be kept in check by immune regulation without causing autoimmunity." (PMID 38596681, 2024). "Insulin is a very early and possibly the earliest target of beta cell reactive CD8+ T cells in the NOD model, and T cell responses to key insulin epitopes condition initiation of autoimmunity against beta cells, with responses to epitopes of other autoantigens including IGRP occurring later." (PMID 39600694, 2024). "Notably, the carbonylation of prolyl-4-hydroxylase beta (P4Hb) serves as an early target of autoimmunity and acts as a pathway that triggers an immune response involving insulin and/or proinsulin." (PMID 38136203, 2023). "Hence, the regenerated insulin-producing cells are vulnerable to ongoing damage due to autoimmunity." (PMID 37663700, 2023). "This is in line with the “overload hypothesis” that suggests that a high insulin load may trigger the onset of autoimmunity and T1D." (PMID 36839302, 2023). "On the other hand, Toxoplasma gondii infection could induce autoimmunity with autoantibodies or other immunologic mechanisms, thus decreasing insulin secretion from pancreatic beta cells." (PMID 36901457, 2023). "Furthermore, insulin signaling has the potential to mediate macrophage polarization in cancer, while mounting evidence supports the role of mTOR signaling in autoimmunity, which is also essential for the activation and proliferation of T‐cells." (PMID 36282125, 2023). "Furthermore, the immune response to coxsackie B virus appears to be incomplete in young children with insulin autoimmunity." (PMID 37231274, 2023).
Autoimmunity (continued). "Herein, we have identified how specific PTMs may arise in T1D and their consequences on both autoimmunity and metabolic pathways, notably glucose sensing and insulin release." (PMID 36389721, 2022). "Only few studies could detect some characteristics associated with autoimmunity in GDM like younger age, lower BMI, lower fasting insulin level, and more frequent need for insulin therapy in pregnancy." (PMID 36093103, 2022). "Neoepitopes derived from citrullination modification of islet proteins, citrullinated GK and/or other unknown glucose-insulin metabolic proteins, compromises immune tolerance to trigger T and B cell autoimmunity." (PMID 35388005, 2022). "On the other hand, the role of IgM in autoimmunity may be more complex as in the so called adaptive tolerance where high affinity memory IgM controls autoimmunity to insulin but our findings seem less related to this mechanism." (PMID 35493489, 2022). "Furthermore, progressed T1D needs replenishment of insulin production besides autoimmunity reversal, as too many beta cells are already lost or defect." (PMID 35903316, 2022). "Although the precise mechanisms of nivolumab-induced T1DM are not fully understood, activated CD8+ T cells have been speculated to evoke autoimmunity against pancreatic beta cells and to destroy them, resulting in insulin exhaustion." (PMID 33892782, 2021). "In this context, the PRE-POINT trial targeted at-risk children carrying a high HLA-associated genetic risk of disease but with no signs of active autoimmunity (i.e. aAb‒) using a daily oral insulin vaccine." (PMID 34447366, 2021). "Using an insulin-derived peptide we tested the role of IgD in autoimmunity." (PMID 34434193, 2021). "Despite many decades of intensive biomedical research, no underlying cause/causes has been brought forward to explain the disease beyond a characteristic adaptive immune response directed against insulin producing cells involving B and T cells, which was later attributed to autoimmunity." (PMID 32927606, 2020). "First, when the loss of IAA positivity reflects events in humoral β-cell autoimmunity, cell-mediated autoimmunity against insulin may still continue." (PMID 32882033, 2020). "In addition, breast milk contains insulin that has a protective effect against autoimmunity as was proved in rats by driving the maturation of gut epithelium as well as in humans by downregulating production of IgG antibodies to bovine insulin." (PMID 33425976, 2020). "Once autoimmunity is triggered by insulin-specific T cells, T cells directed at other antigens may contribute to β cell destruction." (PMID 30899071, 2019). "At least 2 of the 23 patients with no detectable autoimmunity (8%) carried heterozygous pathogenic variants: one previously reported missense variant in the INS gene (p.Gly32Ser) and one novel frameshift variant (p.Val264fs) in the HNF1A gene." (PMID 31365591, 2019). "Patients with suspected IAS must be screened for autoimmunity-related drugs for insulin." (PMID 30462811, 2018). "In summary, the spleen may be close to being an optimal site for islet transplantation because of its rich vascularity, physiological insulin secretion, regulation of immunity including autoimmunity and its potential for islet regeneration." (PMID 29735923, 2018). "Some dietary food proteins have been shown to promote autoimmunity to insulin via cross-reactivity." (PMID 28819632, 2017). "The prevailing paradigm puts autoimmunity at the core of the development of T1D, and impaired insulin secretion may likely occur secondary to the autoimmunity." (PMID 28763444, 2017). "Thus, using two different cohorts and two models of exogenous antigen exposure, we found evidence that children who develop early insulin-targeted autoimmunity have a compromised humoral immune response in early childhood." (PMID 27604323, 2016).